ZNF398 (zinc finger protein 398)
Description:
Functions as a transcriptional activator.
Synonyms: KIAA1339; ZER6; p71-ZER6; p52-ZER6; P51; P71
Tractability: PROTAC: UniProt records ubiquitination sites on it; ubiquitination databases record sites on it.
Gene: Protein-coding gene on chromosome 7 (149,126,416 to 149,183,042, forward strand). Ensembl gene ENSG00000197024.
Subcellular location: Nucleus
Subcellular location (Human Protein Atlas): Nuclear membrane; Nucleoplasm
Pathways (Reactome):
Gene expression (Transcription): Generic Transcription Pathway
Gene Ontology:
Molecular function: protein binding; DNA-binding transcription factor activity, RNA polymerase II-specific; RNA polymerase II transcription regulatory region sequence-specific DNA binding
Biological process: positive regulation of DNA-templated transcription; regulation of DNA-templated transcription; regulation of transcription by RNA polymerase II
Cellular component: nucleus
Genetic constraint (gnomAD): Loss-of-function variants: 24 observed, 43.47 expected, observed/expected ratio (o/e) 0.55, 90% interval 0.4 to 0.78. The synonymous counts are far from expectation, so gnomAD's model fits this gene poorly and the ratio says little. Missense variants: 647 observed, 831.93 expected, observed/expected ratio (o/e) 0.78, 90% interval 0.73 to 0.83. Synonymous variants: 256 observed, 315.95 expected, observed/expected ratio (o/e) 0.81, 90% interval 0.73 to 0.9.
Homologues: Orthologues: macaque ZNF398 (99% identical), chimpanzee ZNF398 (97% identical), rabbit ZNF398 (95% identical), dog ZNF398 (93% identical), rat Zfp398 (92% identical), mouse Zfp398 (91% identical), pig ZNF398 (89% identical), guinea pig ZNF398 (88% identical). Paralogues in human: ZNF777 (44% identical), ZNF746 (35% identical), ZNF407 (20% identical), ZNF527 (19% identical), ZNF408 (19% identical), ZNF467 (19% identical), ZNF17 (19% identical), ZKSCAN7 (19% identical), ZNF287 (19% identical), ZNF774 (19% identical), ZNF333 (18% identical), ZNF416 (18% identical), and 38 more.
Diseases named in the same sentence as ZNF398 in open-access papers:
ZNF398 is named in the same sentence as 12 diseases in open-access papers, as found by Europe PMC text mining. Sharing a sentence is not in itself a finding about the gene and the disease. The quoted sentences say what the papers report.
colon cancer (2 papers, 2022 to 2023). "It was found that ZNF398 was highly expressed in colon cancer, while ZNF398 knockdown resulted in constrained cell proliferation." (PMID 36358661, 2022). "In colon cancer tissues, ZNF398 was overexpressed, and the silencing of ZNF398 resulted in G0–G1 phase obstruction." (PMID 36358661, 2022).
cancer (6 papers, 2018 to 2024). A tumor composed of atypical neoplastic, often pleomorphic cells that invade other tissues. "Owing to its role in cancer and in the regulation of stemness features, the influence of ZER6/ZNF398 on the phenotype of CSCs would be an interesting research direction." (PMID 37492743, 2023).
ZNF398 also shares sentences with these, for which no sentence is quoted: tumor (3 papers); viral infection (3); breast carcinoma (1); colorectal cancer (1); colorectal tumor (1); hepatocellular carcinoma (1); infection (1); Kabuki syndrome 1 (1); lung carcinoma (1); metabolic disorders (1).